NR4A1 (nuclear receptor subfamily 4 group A member 1)
Diseases named in the same sentence as NR4A1 in open-access papers (continued):
Sharing a sentence is not in itself a finding about the gene and the disease.
tumor (continued). "Interestingly, NR4A1 protein in the later stage 231-NR4A1 tumors was decreased to the similar levels as that in the later stage 231-Ctrl tumors, suggesting that the high NR4A1 expression was lost in most of the 231-NR4A1 tumor cells." (PMID 28903348, 2017). "However, when their tumor sizes grew to ̃1 cm in diameter (medium stage), NR4A1 protein in the nuclei of tumor cells was significantly reduced to medium to low levels in individual tumors." (PMID 28903348, 2017). "This could be a consequence of growth selection for the tumor cells with low NR4A1 expression during the tumor progression process in mice." (PMID 28903348, 2017). "Most likely, in early phase, the high level NR4A1 suppressed tumor formation and growth." (PMID 28903348, 2017). "Since NR4A1 plays a role to induce apoptosis through inhibiting Bcl-2, the tumor suppressor role may be partially attributed to its function to mediating apoptosis." (PMID 28903348, 2017). "On the other hand, our study may partially elucidate one of the NR4A1 tumor suppressive roles in TNBC." (PMID 28903348, 2017). "In late phase, some of the tumor cells might lose high NR4A1 expression, escape from its suppression, and acquire growth advantage to become dominant subpopulations in big tumors." (PMID 28903348, 2017). "On one hand, several studies have reported NR4A1 as a tumor suppressor." (PMID 28903348, 2017). "Thus, NR4A1 regulation of these genes in RCC contributes to the tumor phenotype, and inhibition of these genes by C-DIM/NR4A1 antagonists in RCC cells and tumors is an important component of their antineoplastic activity." (PMID 26035713, 2015). "Thus, mitochondrial NR4A1 exhibits tumor suppressor-like activity, and both paclitaxel and peptide mimetics of NR4A1 that bind bcl-2 also activate apoptosis in cancer cells." (PMID 26035713, 2015). "Thus, NR4A1 is unique among orphan nuclear receptors, and the observed pro-oncogenic or tumor suppressor-like activity is dependent on the subcellular location of the receptor." (PMID 26035713, 2015). "Other aspects of NR4A1 functionality that may contribute to tumor development is its ability to promote cell migration, invasion through by promoting MMP-9 expression, inflammation, repair of DNA double-strand breaks and VEGF-induced angiogenesis." (PMID 25269081, 2014). "The elevated RNA abundance for NR4A1 in the mesenchymal state, suggest mesenchymal-like tumor cells may be more sensitive to cisplatin." (PMID 25538889, 2014). "While the primary tumours were positive in 16% (5/31) of cases, only 2% (1/41) of the metastasis were positive for NR4A1 - further confirming its negative association with higher degrees of invasive potential." (PMID 20642837, 2010). "These tumours within each grade that possess demonstrable NR4A1 may therefore be those that are less likely to spread." (PMID 20642837, 2010). "NR4A1 is considered a mediator/regulator of cell survival and apoptosis in tumours." (PMID 20642837, 2010). "As NR4A1 is downregulated in higher grade, more invasive tumours, it was also possible that it may have an effect on the invasive ability of tumour cells." (PMID 20642837, 2010). "As NR4A1 levels decline in higher grade tumours, it was hypothesised that NR4A1 may have an adverse effect on the migratory ability of tumour cells." (PMID 20642837, 2010). "Since the levels of NR4A1 inversely correlate with tumour grade and invasiveness, it was important to determine whether NR4A1 also has the ability to reduce tumour cell invasion." (PMID 20642837, 2010). "RXR may also exert its effects on tumor cell survival and growth by partnering with PPARγ and/or NR4A1." (PMID 17407572, 2007). "Although NR4A1 is highly expressed in normal breast tissues but is decreased in tumorous breast tissues, the biological function of NR4A1 in BC has not been clearly explained, and it remains controversial whether NR4A1 has tumor-suppressive or tumor-promoting activity." (PMID 40164686, 2025).
tumor (continued). "In addition to the use of agonists, increasing the expression of NR4A1 in cells might be a more efficient strategy for exerting the tumor-suppressive effect of NR4A1 in BC." (PMID 40164686, 2025). "Likewise, a recent study reported double deletion of NR4A1/NR4A2 in CD8+ tumor-infiltrating lymphocytes (TILs) resulted in murine tumor eradication after transfer as well as expansion of TSL population with increased chromatin accessibility of several stem-like/memory-related genes." (PMID 39211052, 2024). "In studies on tumor-inoculated mice, it was shown that CAR-T cells deficient in both TOX and TOX2, or with triple KO of NR4A1, NR4A2, and NR4A3, had a greater anti-cancer activity and improved animal survival; therefore, targeting the TOX/NR4A axis may reduce the depletion of CAR-T cells in TME." (PMID 37296906, 2023). "However, several studies also indicated that NR4A1 has proapoptotic and tumor inhibitory effects." (PMID 36566195, 2022). "For another, maybe it can be extended the roles of NR4A1 to other aspects of tumor metabolism." (PMID 36052242, 2022). "Therefore, it can be speculated that NCOR2 may affect the biological function of tumour cells by regulating the expression of BDNF through NR4A1." (PMID 36497280, 2022). "In addition, NR4A1 is involving in amino acid metabolism and tumor immunity by metabolic processes." (PMID 36052242, 2022). "Besides the amino acid metabolism, NR4A1 also participates in tumor immunity." (PMID 36052242, 2022). "However, it is still unclear whether nuclear localization of NR4A1 through drugs that block nuclear export of NR4A1 confers tamoxifen resistance or tumor progression, thus requiring further investigation." (PMID 34209871, 2021). "A recent study using Nr4a1-deficient mice, which lack Ly6Clow monocytes, demonstrated that in the absence of Ly6Clow monocytes tumor metastatic burden significantly increased but could be reduced by adoptive transfer of Nr4a1-proficient LyC6low monocytes." (PMID 31402908, 2019). "In addition, cytoplasmic NR4A1 levels and tumor stage were found to be borderline significant." (PMID 30266952, 2018). "The recent development of Nr4a1 agonists that directly bind and activate Nr4a1 may be useful pharmacological tools to increase Creb3l1 expression in tumor cells, but our data shows that this would certainly depend on the methylation status of the Creb3l1 promoter." (PMID 29311806, 2017). "In addition, low and moderate levels of NR4A1 protein was detected in the early stage 231-Ctrl tumors and the late stage 231-Ctrl and 231-NR4A1 tumors, which could be contributed from the stromal and immune cells in the tumor microenvironment." (PMID 28903348, 2017). "Since cytoplasmic NR4A1 has been shown to mediate apoptosis in several cancer cell lines, its reduced expression in higher grade and metastatic tumours may possibly contribute to the survival of such tumour cells." (PMID 20642837, 2010). "similarly performed RNA-seq using tumor and tumor-adjacent tissues from four LUAD patients and found low expression of NR4A1 in the cancer tissues." (PMID 40666103, 2025). "This study provides new insights into the molecular mechanisms underlying the progression of GBM, emphasizing the role of SERPINE1 and its interaction with NR4A1 in promoting EMT and tumor invasion." (PMID 41584614, 2025). "IFN-γ plays an important role in macrophage activation, phagocytosis and antigen presentation; thus, the NR4A1-mediated suppression of IFN-γ limits CD8+ T cell activation and anti-tumor immune responses." (PMID 40508074, 2025). "In contrast, in most solid tumors, both NR4A1 and NR4A2 exhibit pro-oncogenic activity, whereas, in limited studies, NR4A3 exhibits either minimal activity or acts as a tumor suppressor." (PMID 40332813, 2025). "The most downregulated genes contained known tumor suppressors (ZNF831, AKNA, NR4A1, ARHGAP9, ZBTB16) and regulators of immune response (NLRC5, WDFY4, RASGRP2, IKZF1)." (PMID 39794830, 2025).
tumor (continued). "Intriguingly, NR4A1-dependent LY6Clo NCMs migrate toward tumor colonies using the CX3CR1/CX3CL1 axis, where they have been suggested to mediate tumor lysis." (PMID 39545417, 2024). "We also analyzed NR4A1 protein in MC38 tumors with mice treated with vehicle, celastrol, and NR-V04 after a total of 8 doses for 4 wk in tumor-bearing mice." (PMID 38334978, 2024). "GrB+ B cells from tumor samples exhibited slightly higher expression levels of LAIR1 and NR4A1 but a lower level of CD69 expression." (PMID 38386050, 2024). "Using the gene list expressed in these hotspots within the high-violence tumor samples, functional enrichment analysis revealed an upregulation of glucocorticoid biosynthesis in AKR1C1, AKR1C2, and NR4A1 overexpression, indicating altered cortisol synthesis." (PMID 38912926, 2024). "Previous studies using mouse MC-38 cells show that in a syngeneic immunocompetent mouse model using this cell line as xenograft results in tumor growth and also splenomegaly and thus the effects of CDIM/NR4A1 antagonists in the spleen can also be investigated." (PMID 37847301, 2023). "Using cancer therapeutics response analysis, we found that high expression levels of NR4A1 were sensitive to OSI-930, a tyrosine kinase inhibitor with anti-tumor effects." (PMID 37564873, 2023). "Conjointly, these results demonstrate that NR4A1 promotes PTC cell proliferation and tumor aggressiveness." (PMID 35110542, 2022). "NR4A1 activates TGF signaling and promotes EMT in tumor cells, whereas the present study in HSCs differs from those in tumor cells." (PMID 35600274, 2022). "Both NR4A1 and NR4A3 are silenced in AML and display tumor-suppressing qualities suppressing MYC activity." (PMID 33634114, 2021). "Recent studies strengthen this significant body of work, further demonstrating that NR4A1 is essential for VEGF-A-induced pathological angiogenesis, tumor growth, and metastasis in vivo." (PMID 33634114, 2021). "Conversely, expression of the genes associated with NK cell exhaustion, such as PDCD1, CTLA4, KLRC1, NR4A1, and SOCS3, was upregulated in tumor-infiltrating NK cells." (PMID 34535671, 2021). "Hence, its reduced expression in tamoxifen-resistant tumor cells may contribute to apoptosis and cell survival, and translocation of NR4A1 to the cytoplasm from the nucleus by various agents, including cytosporone B and C-DIM may serve as a unique therapeutic strategy." (PMID 34209871, 2021). "The authors also interrogated NR4A1 function in a mouse model of lymphoma by deleting it (Nr4a1DKO) in CD8+ T cells and transforming them into tumor-bearing mice." (PMID 32823814, 2020). "EZR-negative tumor cells also show the significant upregulation of CD109, ID4, ST8SIA1, and NR4A1 genes." (PMID 32679794, 2020). "Nr4a1 knockdown in C57BL/6 nude mice with RKO cells xenografts had decreased tumor volume and final tumor weight." (PMID 31683815, 2019). "NR4A1(nuclear receptor subfamily 4 group A member 1) was validated to be targeted by miR-377 and PCH4 and act as a tumor promoter in OSCC." (PMID 31141819, 2019). "MCF-7, MDA-MB-231 and SKBR3 cell lines had decreased cell number and tumor weigh when treated with the Nr4a1 antagonists DIM-C-pPhCO2Me and DIM-C-pPhCN, as well as with Nr4a1 knock down." (PMID 31683815, 2019). "Advanced tumour stage (3 or 4), the NGCB subtype, increasing age, and low cytoplasmic NR4A1 levels present poor prognostic factors." (PMID 30266952, 2018). "Several small molecules that significantly inhibit tumor cell proliferation and promote apoptosis have been reported in the literature, and these small molecules, including C-DIM, interact well with NR4A1." (PMID 29498706, 2018). "The findings of the two experimental studies described in the section on tumor growth and metastasis, suggest that FPR2-ERK signaling, TGF-β, and NR4A1 are candidate targets for novel treatments of overt metastatic disease." (PMID 30213113, 2018).
tumor (continued). "The events triggered by exosomes involve Nr4a1 induction in BM monocytes precursors, leading to PMo expansion, recruitment, and differentiation of TRAIL-positive tumor-reactive macrophages, which kill and phagocytize the tumor cells." (PMID 29105655, 2017). "Other genes similarly regulated include DUSP1, EGR1, EGR2, JUN, and NR4A1, which are components of the TTP-low tumor gene signature, again linking TTP levels and innate immunity." (PMID 25541715, 2014). "NR4A1 reduced tumour cell migration, since 61 ± 2.1% (mean ± SE, n = 3, P < 0.001) and 44 ± 5% (mean ± SE, n = 3, P < 0.001) of PMC42-NR4A1 cells and ZR75-1-NR4A1 cells, respectively, migrated compared with control cells." (PMID 20642837, 2010). "In contrast, NR4A1 and CSRNP1 exhibited markedly lower expression in the tumor group." (PMID 41502527, 2025). "Moreover, JUNB (JunB proto-oncogene) and NR4A1 (nuclear receptor subfamily 4 group A member 1 gene) can also regulate the functional state of T cells in the TIME, serving as targets of tumor immunotherapy." (PMID 40574864, 2025). "Studies in this laboratory have shown that C-DIM compounds act as functional NR4A1 inverse agonists in cancer cells and inhibit TNBC cell and tumor growth and the EC50 values for inhibiting tumor growth in athymic nude mice bearing MDA-MB-231 cells by DIM-3,5 analogs is <1 mg/kg/day." (PMID 41184246, 2025). "Studies in this laboratory have shown the CDIM compounds that act as functional NR4A1 inverse agonists in cancer cells inhibit TNBC cell and tumor growth and the EC50 values for inhibiting tumor growth in athymic nude mice bearing MDA-MB-231 cells by DIM-3,5 analogs is < 1 mg/kg/day." (PMID 40313760, 2025). "Among these processes, the loss of NR4A1 enhances the proliferative ability of luminal BC cells, which is consistent with the suppressive role of NR4A1 in inhibiting basal-like and HER2-positive BC cells, confirming the tumor-suppressive role of NR4A1 in the inhibition of BC growth." (PMID 40164686, 2025). "While NR4A1-dependent N-NCMs are naturally abundant under steady-state conditions in WT hosts, the NOD2-dependent subset can be pharmacologically induced to enhance tumor immunity against a variety of metastases." (PMID 39545417, 2024). "NR4A1 was markedly upregulated in tumor-infiltrating NK cells, which reduced the efficacy of anti-PD-1 therapy through modulation of the IFN-γ/p-STAT1/IRF1 signaling pathway, leading to dysfunctional tumor-infiltrating NK cells." (PMID 38999981, 2024). "We have been actively developing other E3-recruiting NR4A1 PROTACs, but at the current stage, none of those different PROTACs exhibit better tumor suppression and safety profile than NR-V04." (PMID 38334978, 2024). "However, triple knockout of Nr4a (including Nr4a1, Nr4a2, and Nr4a3) in CAR-T cells promoted tumor regression and prolonged the survival of tumor-bearing mice." (PMID 37596653, 2023). "Nurr77 (also known as NR4A1, NGFI-B, TR3, and NAK), belonging to the nuclear hormone receptor superfamily, the NR4A subfamily, plays an important role in DNA repair, metabolism, tumor genesis, and inflammation." (PMID 36770929, 2023). "In contrast, tumor T cells’ DEGs coded for heat shock proteins, such as HSPA6, HSPA1A, and HSPA1B in addition to genes related to T cell development and function, such as NR4A1 and NR4A2." (PMID 35534852, 2022). "Indeed, the Nr4a triple-knockout (Nr4a1, Nr4a2 and Nr4a3) in CAR TILs promoted tumor regression and prolonged the survival of tumor-bearing mice." (PMID 34639168, 2021). "They found that in the absence of NR4a1, Teff exhibited significantly better tumor infiltration and effector function at eliminating tumors than WT CD8+ T cells and low levels of PD-1 and TIM-3." (PMID 32823814, 2020).
tumor (continued). "At the same time, the transcript levels of genes encoding for claudin-3 (CLDN3), the nuclear receptor subfamily 4 group A member 1 (NR4A1), and the transforming growth factor β (TGFB2) related to angiogenesis, hypoxic response and tumor invasion were up-regulated." (PMID 32664456, 2020). "Nr4a1 knock down decreased PC3 cell line proliferation, DU145 and PC3 cells were also Nr4a3 sensitive, with Nr4a3 overexpression decreasing proliferation and tumor size and Nr4a3 proliferation increasing proliferation." (PMID 31683815, 2019). "Transcription factor binding motif enrichment analysis identifies several immune-related transcription factors, including three exhaustion-related genes (NR4A1, BATF, and EGR2) and VDR, which potentially play an important regulatory role in tumor-reactive CD8+ T cells." (PMID 31892342, 2019). "NR4A1 is a nuclear protein expressed in RD and Rh30 cells, and there is evidence from publically available array data from RMS tumors that NR4A1 mRNA is overexpressed in tumor vs. non-tumor tissue." (PMID 27144436, 2016). "1,1-Bis(3-indolyl)-1-(p-substituted phenyl)methane (C-DIM) analogs containing p-hydroxyl (DIM-C-pPhOH) and p-carboxymethyl (DIM-C-pPhCO2Me) substituents are NR4A1 ligands that decreased NR4A1-dependent transactivation in RMS cells and inhibited RMS cell and tumor growth and induced apoptosis." (PMID 27144436, 2016). "In contrast, we observe that NR4A1 regulates a transcriptional profile dominated by proliferative genes, specifically a core MYC oncogenic signature, which is likely the primary mechanism of tumor suppression by NR4As." (PMID 26938745, 2016). "Thus, both knockdown of NR4A1 by RNAi or treatment with C-DIM/NR4A1 antagonists inhibited RCC cell and tumor growth." (PMID 26035713, 2015). "Both NR4A1 knockdown and the NR4A1 antagonists inhibited ACHN and 786-O cell proliferation and transactivation, and DIM-C-pPhOH also inhibited tumor growth in athymic nude mice bearing ACHN cells as xenografts and siNR4A1 and NR4A1 antagonists also induced apoptosis in these cell lines." (PMID 26035713, 2015). "As several studies have previously suggested that NR4A1 induces tumour cell apoptosis, the Annexin V assay was performed - showing that, in the case of the tumour lines tested, NR4A1 did not affect cell apoptosis." (PMID 20642837, 2010). "MCF-10A and 226L normal mammary epithelial cells as well as the tumour lines PMC42, ZR-75-1 and MDA-MB-231 were transduced with full-length NR4A1, and the ability of NR4A1-overexpressing cells to migrate was tested using scratch wound or transwell migration assays." (PMID 20642837, 2010). "Since our data show that NR4A1 expression is increased in primary tumours compared with normal breast we examined its biological role in breast biology." (PMID 20642837, 2010). "Hence, we review the literature on the expression of NR4A1 in different immune cells within the TME and examine how different immune-modulatory genes regulated by NR4A1 alter the activity of immune cells in both a pro- and anti-tumor fashion." (PMID 40508074, 2025). "Similarly, NR4A1 expression was significantly lower in tumor tissues than in paired nontumor tissues." (PMID 40164686, 2025). "Strikingly, treatment with metformin might reduce tumor growth, mainly by inducing the expression of a set of genes FOSB, EGR1, ZFP36, GPR183, ATF3, and NR4A1 which are involved in DNA-binding transcriptional activation, response to hormones and the Dcp1-Dcp2 mRNA-decapping complex." (PMID 39026155, 2024). "Notably, in AML mice models, both NR4A1 and NR4A3 have been identified as tumor suppressors." (PMID 38334807, 2024). "Interestingly, in comparison to wild-type CAR T cells, the transfer of NR4A1, NR4A2, and NR4A3 triple knockout CAR T cells to tumor-bearing mice decreased the proportion of highly exhausted CAR T cells among the tumor-infiltrating lymphocytes and led to a better prognosis." (PMID 35606821, 2022).